PAPPA (pappalysin 1)
Diseases named in the same sentence as PAPPA in open-access papers (continued):
Sharing a sentence is not in itself a finding about the gene and the disease.
cancer (46 papers, 2008 to 2026). A tumor composed of atypical neoplastic, often pleomorphic cells that invade other tissues. "Our preliminary results seem to suggest that PAPPA expression can be performed on indeterminate FNAC before the molecular tests in order to identify patients at risk of having cancer and that will benefit from genetic analysis." (PMID 35563038, 2022). "Bioinformatic modeling led to the identification of pregnancy-associated plasma protein A (PAPPA) as novel cancer-promoting stromal factor secreted by HSCs, which is related to advanced-stage HCC." (PMID 32188134, 2020). "The gene showing the highest differential expression in the cancer stem cell population, by up to four-fold, was that encoding the secreted metallo-protease Pappalysin A (PAPPA)." (PMID 18492237, 2008). "The gene showing the highest differential expression in the cancer stem cell population was that encoding PAPPA." (PMID 18492237, 2008). "Recently, PAPPA expression has been linked with development of several cancers." (PMID 34350538, 2022). "Pregnancy-associated plasma protein A (PAPPA) is a metalloproteinase that regulates insulin-like growth factor availability via cleavage of IGF-binding proteins, yet its role in cancer remains incompletely understood." (PMID 41892220, 2026). "In cancer tissues from CC patients, circ-PAPPA expression was measured and its relationship with patients’ clinical features was analyzed." (PMID 39951875, 2025). "Studies have demonstrated that PAPPA acts as an oncogene by promoting cancer cells proliferation, migration and invasion." (PMID 35563038, 2022). "In literature, the involvement of PAPPA in cancer development and progression has been explored in multiple cancer types supporting its possible role as oncogene." (PMID 34350538, 2022). "Among them, COL1A1, COL1A2, MT-CYB, CCT5, and PAPPA have been reported to be closely related to cancer." (PMID 35360863, 2022). "Of these, 10 were expressed in cancer-associated fibroblasts (CAFs) and were increased in ILC compared to IDC in bulk gene expression datasets, with PAPPA and TIMP2 being associated with better survival in ILC but not IDC." (PMID 35205651, 2022). "PAPPA content in cancer cell lines is comparable (in cases of A549 and Calu-1) or less (in case of H460, H596, H1299, H1792 and H19444) than HBE cell lines in general." (PMID 23152806, 2012). "Higher serum level of PAPPA was observed in mice implanted with cancer cells over-expressing PAPPA when compared with control cells." (PMID 23152806, 2012). "It is conceivable that PAPPA neutralizing antibody or its specific protease inhibitor would have beneficial effect on cancer therapy with additive effect of a healthier heart." (PMID 23152806, 2012). "Moreover, evidences suggest that PAPPA activity promotes cancer proliferation, invasion, migration and metastasis." (PMID 34350538, 2022). "Cancer-associated genes LIF and PAPPA are possible targets of miR-500a-3p." (PMID 28952053, 2018). "Among the 10 paracrine factors were both known and unknown cancer promoting stromal factors, the former including Placental Growth Factor (PGF) and Periostin (POSTN), while Pregnancy-Associated Plasma Protein A (PAPPA) was among the latter." (PMID 26020769, 2015). "Since HCC mostly develops in cirrhotic liver tissue, inhibition of PAPPA could not only affect HCC cells but also prevent the formation of a protumorigenic soil for cancer cells." (PMID 26020769, 2015). "PAPPA knockout mice were observed to have reduced incidence of spontaneous cancers." (PMID 23896451, 2013). "Accumulating preclinical evidences support the idea that PAPPA may play a role in cancer." (PMID 23896451, 2013). "Accumulating evidences support the notion that PAPPA may play a role in cancer." (PMID 23896451, 2013). "Given the role of CAFs in interacting with cancer cells via growth factors, inflammatory ligands, and ECM proteins,we investigated the correlation between MGP, COL8A2, and PAPPA with CAF markers." (PMID 37777759, 2023).
cancer (continued). "In cancer genomes, frequent substitutions at glycosylation sites are apparent in epidermal growth factor receptors and oncogenes EGFR and ERBB3, as well as PAPPA, a secreted protein involved in the activation of insulin-like growth factor pathways." (PMID 33834021, 2021). "PAPPA can act as an autocrine or paracrine regulator of IGF action and the proposed mechanism for enhancing cancer migration is by increasing IGF release following the proteolysis of IGFBP4." (PMID 25940796, 2015). "Less is known about this pathway to date; however, the presence, interaction, and potency of IGFBPs with this pathway and both PAPPA and MMP2 could shed light on the complex role of this pathway in cancers." (PMID 39854135, 2025). "Even though the role of PAPPA in cancer has not gathered much attention, IGF-1, the pervasive growth factor whose local bioavailability it regulates, has long been an intense interest for cancer researchers." (PMID 23896451, 2013). "PAPPA secretion changes in both H1299 and A549 has no notable effect on cancer cell growth in vitro in culture, due to the fact that cell culture lacks of a proper microenvironment where IGFs in culture medium are in free access to their receptors." (PMID 23152806, 2012). "The role of PAPPA as a local regulator of IGF bioavailability through cleavage of IGFBPs has been well documented, and the IGF axis was identified as one of the molecular networks involved in the formation, progression and metastatic spread of many cancer types, including MPM." (PMID 23896451, 2013). "Interestingly, H1792/PAPPAov cells showed a significant reduction of cell growth when compared with its vector control cells, suggesting that increases of non-secretive, intracellular PAPPA may exert distinct roles in cancer cell growth." (PMID 23152806, 2012). "PAPPA (nonhub) and MMP2 (hub) have been introduced as cancer biomarkers." (PMID 39854135, 2025).
cardiovascular diseases (21 papers, 2010 to 2025). "These initial observations were confirmed by other groups that found an alteration in the plasma concentration of STC2 and pregnancy-associated plasma protein A (also known as pappalysin-1 or PAPP-A or PAPPA1) in DM2 patients suffering from cardiovascular diseases." (PMID 41155293, 2025).
genetic disorders (4 papers, 2015 to 2022). "Further, PAPPA has long been recognised as a useful biomarker of fetal genetic disorders and adverse pregnancy outcomes." (PMID 25940796, 2015). "PAPPA is well recognized as a marker for fetal genetic disorders and adverse pregnancy outcomes, however, there physiological role of PAPPA2 remains unclear." (PMID 26161641, 2015).
infection (2 papers, 2021 to 2025). The state of being infected such as from the introduction of a foreign agent such as serum, vaccine, antigenic substance or organism. "However, our screening also identified invasion- and migration-related genes that were not significantly modulated upon infection (i.e., PAPPA, SNAIL, MMP9, MMP11, ICAM1, CTNNB1, and CDH2)." (PMID 41450565, 2025).
PAPPA also shares sentences with these, for which no sentence is quoted: trisomy 21 (25 papers); Stillbirth (23); aneuploidy (11); coronary artery disease (11); Miscarriage (10); myocardial infarction (9); placental insufficiency (8); type 2 diabetes (8); endothelial dysfunction (6); macrosomia (5); placental abruption (5); trisomy 18 (5); carotid atherosclerosis (4); Glucose intolerance (4); pregnancy induced hypertension (4); acute myocardial infarction (3); asthma (3); cerebrovascular diseases (3); chromosomal disorder (3); diabetic nephropathy (3); growth disorders (3); heart failure (3); insulin-dependent diabetes (3); malignant pleural mesothelioma (3); neural tube defect (3); placenta previa (3); placental disorders (3); stable angina (3); Stroke (3); adenocarcinoma (2).
A further 113 diseases each share a sentence with PAPPA in 2 papers or fewer.